TIMP2 (TIMP metallopeptidase inhibitor 2)
Diseases named in the same sentence as TIMP2 in open-access papers (continued):
Sharing a sentence is not in itself a finding about the gene and the disease.
ovarian carcinoma (continued). "In ovarian cancer cell lines, TIMP-2 is a potent inhibitor of MT1-MMP and can significantly reduce invasion through inhibiting matrix degradation." (PMID 33810259, 2021). "In that connection, we previously reported and report in this study upregulation of TIMP-2 mRNA and protein levels in response to chemotherapy treatment in ovarian cancer cell lines." (PMID 35047406, 2021). "In this study, we also show that cisplatin (CIS) and paclitaxel (PTX) enhanced the expression of TIMP-1 and TIMP-2 at the protein level in all four ovarian cancer cell lines studied." (PMID 35047406, 2021). "Through down-regulation of MMP2 and 9 paralleled by up-regulation of their inhibitors (TIMP2 and 3), Pug attenuated the migratory potential of human cervical and ovarian cancers." (PMID 34444893, 2021). "The knock down of TIMP-2 resulted in enhanced cell proliferation and increased sensitivity to chemotherapy treatments in ovarian cancer and Fallopian tube epithelial cells." (PMID 33023532, 2020). "Enhanced proliferation and invasion by knockdown of TIMP-2 in ovarian cancer cell lines is consistent with previous studies that have shown that overexpression of TIMP-2 reduced invasion and proliferation in cells." (PMID 33023532, 2020). "In the first instance, we show that knock down of TIMP-2 in ovarian cancer cells results in enhanced proliferation and invasion, processes essential for the progression of cancer." (PMID 33023532, 2020). "As an endogenous inhibitor of MMPs, TIMP2 was decreased in various types of cancer, including ovarian cancer, cervical cancer, and OS." (PMID 31383784, 2019). "There is already established scientific evidence linking the decrease in TIMP2 with the progress of cancers, including ovarian cancer, cervical cancer, OS, however, the specific mechanisms of TIMP2 in OS was still unclear." (PMID 31383784, 2019). "In a third study an increase of TIMP-2 expression in the stroma and tumor compartment was positively correlated with a better survival rate of patients with ovarian cancer." (PMID 29393911, 2018). "The results indicate that downregulation of FBLN5 in ovarian cancer was accompanied by dramatic induction of MMP-9 and loss of its inhibitor, TIMP2." (PMID 29581841, 2018). "In conclusion, EZH2 promotes ovarian cancer migration and invasion via the epigenetic silencing of TIMP2 by H3K27me3 and DNA hypermethylation, which leads to the activation of MMP2 and MMP9." (PMID 28620234, 2017). "In support, overexpression of Ezh2 is shown to increase recruitment of Dnmts at the TIMP2 promoter in ovarian cancer." (PMID 29261844, 2017). "About 15 studies have been published on the prognostic value of MMP-2, MMP-7, MMP-9, MT1-MMP, TIMP-1 or TIMP-2 in ovarian cancers, but the results remain controversial." (PMID 22200690, 2012). "We therefore, used a translational approach to analyze the epithelial and stromal expressions of MMP-2, MMP-7, MMP-9, MT1-MMP, TIMP-1 and TIMP-2 in advanced epithelial ovarian cancers and to assess their prognostic value." (PMID 22200690, 2012). "We set out to analyze the epithelial and stromal expression of MMP-2, MMP-7, MMP-9, MT1-MMP, TIMP-1 and TIMP-2 in advanced epithelial ovarian cancers and to assess their prognostic value." (PMID 22200690, 2012). "The roles of MMPs and TIMPS in ovarian cancer are further confounded by immunohistochemical studies looking at expression of TIMP2 in ovarian cancer tissues." (PMID 22022379, 2011). "In summary, arming with TIMP2 appears to be useful for the treatment of disseminated ovarian cancer, as it increased survival in vivo." (PMID 22022379, 2011). "In this paper we show that co-culture of ovarian carcinoma cells with fibroblasts resulted in an enhanced release of proMMP-2 and TIMP-2 into the culture medium." (PMID 10408832, 1999). "Thus, in SKOV-3 cells, GnRH2 inhibits ovarian cancer invasion by regulating the balance of MMP2/TIMP2, and disrupting AKT-mediated proteolysis and invasion." (PMID 38260130, 2023).
ovarian carcinoma (continued). "Ovarian cancer cells with less availability of TIMP-2 and more of MMPs as in the case of gRNA1 cells, may generate aggressive tumours with a greater degree of tumour burden and metastasis resulting in infiltration to the peritoneal organs." (PMID 36585738, 2022). "Exosomes derived from SKOV-3 ovarian cancer cells altered the expression of only the TIMP2 gene." (PMID 36012171, 2022). "These in vivo results suggests that the tumorigenic phenotype in ovarian cancer cells may vary depending on the level of expression of TIMP-2; it can be provoked and aggravated by a pronounced deficiency of TIMP-2 expression, as shown in gRNA1 cells." (PMID 36585738, 2022). "Overall, the staining of these tumours indicates that TIMP-2 expression was reduced in the tumours originating from gRNA1 and gRNA2 cells, compared to parental and control tumours and these tumours were of human ovarian cancer origin (express CA125)." (PMID 36585738, 2022). "TIMP2 regulates metastasis in several cancers, including cervical, lung and ovarian cancer." (PMID 36291151, 2022). "However, we also demonstrate that knock down of TIMP-2 enhances the chemosensitivity of ovarian cancer cells, a process that potentially contradicts processes involved with tumourigenesis." (PMID 33023532, 2020). "These MT1-MMP-mediated functions may explain the enhanced invasion observed in the ovarian cancer cell lines with decreased TIMP-2 expression after siRNA treatment." (PMID 33023532, 2020). "In the chemotherapy treatment scenario, it is possible that the chemotherapy-induced acute secretory process, which causes the release of soluble factors (including TIMP-2), may control the activation of STAT3 in ovarian cancer cells." (PMID 33023532, 2020). "We also demonstrate for the first time that suppression of TIMP-2 expression in Fallopian tube secretory epithelial cells and two ovarian cancer cell lines by an in vitro transient knock down (siRNA) modulates ovarian cell proliferation, invasion and sensitivity to chemotherapy." (PMID 33023532, 2020). "High mRNA expression of MMP-2, MMP-9, MT1-MMP and TIMP-2 in primary ovarian tumors and stromal compartments was associated with poor survival in ovarian cancer patients, suggesting that MMP-2, MMP-9, MT1-MMP and TIMP-2 are valid markers of poor survival in advanced-stage ovarian carcinoma." (PMID 29393911, 2018). "In addition, both 5Aza treatment and DNMT1 and DNMT3A knockdown increased TIMP2 mRNA and protein expression and reduced DNA methylation of the TIMP2 promoter, suggesting that TIMP2 expression is down-regulated by DNA methylation in ovarian cancer cells." (PMID 28620234, 2017). "This evidence suggests a significant contribution of TIMP2 to EZH2 function in ovarian cancer." (PMID 28620234, 2017). "Interestingly, EZH2 has a similar functional spectrum to that of TIMP2 with regard to the regulation of tumor biology and plays an active role in metastasis and angiogenesis in ovarian cancer." (PMID 28620234, 2017). "EZH2 promoted ovarian cancer invasion and migration, which could be largely reversed by TIMP2 down-regulation in vitro and in vivo." (PMID 28620234, 2017). "In an effort to develop a successful CRAd geared toward the treatment of disseminated ovarian cancer, we proposed that arming it with TIMP2 would augment the therapeutic efficacy of the CRAd by inhibiting tumor progression through both MMP-dependent and MMP-independent pathways." (PMID 22022379, 2011). "As initiation of inflammation and its sustained level is a major contributor of ovarian tumorigenesis, it can be postulated that the differences in the ratios of TIMP-2 and MMPs may be a tipping point in controlling the tumorigenic behaviour of ovarian cancer cells." (PMID 36585738, 2022). "However, epigenetic silencing of TIMP2 can promote invasion of ovarian cancer (OC)." (PMID 34781885, 2021). "Furthermore, higher tissue levels of TIMP-2 marked a favorable prognosis in ovarian cancer." (PMID 32560557, 2020).
ovarian carcinoma (continued). "On the other hand, a recent study has reported that increased TIMP-2 expression in the stromal compartment, but not in tumor cells, is associated with an enhanced response to cisplatin and paclitaxel-based chemotherapy in ovarian cancer patients." (PMID 29393911, 2018). "Similarly, the enhanced migration and invasion of ovarian cancer cells induced by ectopic EZH2 expression could be relieved by co-expression of TIMP2." (PMID 28620234, 2017). "The combination of the pan-PI3K inhibitor LY294002 with cisplatin effectively inhibits the proliferation and migration of ovarian cancer cells by downregulating the expression of Matrix Metalloproteinase-2 (MMP-2), TIMP1, and TIMP2." (PMID 40656893, 2025). "For instance, Wanget al. revealed that miR-149-3p promoted resistance to DDP in ovarian cancer by regulating CDKN1A and TIMP2." (PMID 38477044, 2024). "Approximately 70–90% knock down of TIMP-2 expression were confirmed in T2-KD, gRNA1 and gRNA2 OVCAR5 ovarian cancer cells at the protein level." (PMID 36585738, 2022). "In epithelial ovarian cancer cell lines, EZH2 levels correlate inversely with TIMP2 levels via the EZH2 methylation of H3K27 on the TIMP2 promoter." (PMID 36359771, 2022). "Our results suggest that the inhibition of TIMP-2 by siRNA and CRISPR/Cas-9 modulate the expression of MMP-2 and MMP-14 and reprogram ovarian cancer cells to facilitate proliferation and invasion." (PMID 36585738, 2022). "A study also reported that EZH2 facilitates TIMP2 (Tissue Inhibitor of Metalloproteinase 2) and ADP-Ribosylarginine hydrolase 1 (ARH1) by DNA methylation and H3K27me3, which leads to ovarian cancer metastasis." (PMID 36092905, 2022). "The growth and spread of ovarian cancer can be orchestrated by MMP-14 in conjunction with other molecules including MMP-2, TIMP-2 and the integrins." (PMID 34344453, 2021). "This study aimed to determine the role of TIMP-2 in ovarian cancer progression and chemoresistance by reducing TIMP-2 expression in vitro in Fallopian tube secretory epithelial (FT282) and ovarian cancer (JHOS2 and OVCAR4) cell lines." (PMID 33023532, 2020). "We transiently suppressed the TIMP-2 expression by siRNA in a Fallopian tube secretory epithelial cell line, FT282, and two ovarian cancer cell lines, JHOS2 and OVCAR4." (PMID 33023532, 2020). "Both MMP-2 and MMP-9 were enhanced in one of the ovarian cancer cell lines (SKOV3) in response to gonadotropins, while TIMP-1 and TIMP-2 were down regulated, suggesting an inverse relationship between MMPs and their endogenous inhibitors." (PMID 29393911, 2018). "EZH2 suppressed TIMP2 expression and increased MMP activity, which subsequently promoted ovarian cancer cell migration and invasion in vitro and in vivo." (PMID 28620234, 2017). "Previously, we developed and determined the therapeutic potential of a TIMP2-armed CRAd, Ad5/3-CXCR4-TIMP2, for ovarian cancer therapy." (PMID 22022379, 2011). "Furthermore, miR-149-3p was shown to inhibit EMT by targeting TIMP metallopeptidase inhibitor 2 (TIMP2) and cyclin-dependent kinase inhibitor 1A (CDKN1A) mRNAs in ovarian cancer." (PMID 38396852, 2024). "We have previously shown, that unlike the vector control cells, siRNA knockdown of TIMP-2 in OVCAR4 ovarian cancer cell line rendered the transfected cells sensitive to PTX treatment." (PMID 36585738, 2022). "Additionally, the authors, in their investigations on cervical and ovarian cancer cells, observed a Pug-induced reduction in matrix metalloproteinases (MMP2 and 9) paralleled by a rise in their inhibitors (TIMP2 and 3)." (PMID 34444893, 2021). "DCN (Decorin), AKT3 (AKT Serine/Threonine Kinase 3), and TIMP2 (tissue inhibitor of metalloproteinases 2) are the other novel candidate target genes for miR-182 involved in the regulation of ovarian cancer biological processes." (PMID 34721577, 2021).
ovarian carcinoma (continued). "However, the concurrent enhanced expression of TIMP-2, -3 and MMP-9, -11, -14 observed in ovarian carcinomas is conflicting with the potential inhibitory actions of the TIMPs on MMPs and requires further investigation." (PMID 35047406, 2021). "This indicates that TIMP-2 may mediate proliferation in FT282 and ovarian cancer cell lines through different cell cycle mediated mechanisms." (PMID 33023532, 2020). "By using siRNA, we examined the effect of TIMP-2 knock down (T2-KD) on MT1-MMP and MMP-2 expression levels, proliferation, invasion and chemosensitivity in Fallopian tube secretory epithelial cells and two ovarian cancer cell lines." (PMID 33023532, 2020). "We have recently demonstrated that both viral replication and oncolytic potency were not compromised in both SKOV3.ip1 and OV-4 human ovarian cancer cells by arming with TIMP2." (PMID 22022379, 2011). "In ovarian cancer, high mRNA expression of MMP-2, -9, -14 and TIMP-2 was reported in ovarian tumors, and correlated with low survival in patients, indicating that the expression of these genes may act as suitable nominators of survival in advanced-stage patients." (PMID 35047406, 2021). "In that context, chemotherapy treatment of ovarian cancer cells in which TIMP-2 was knocked down failed to activate Stat3, implying that TIMP-2 and Stat3 may be critical regulators of chemoresistance." (PMID 35047406, 2021).
prostate carcinoma (35 papers, 1994 to 2023). A carcinoma that arises from epithelial cells of the prostate gland. "For example, TIMP-2 is hypermethylated and silenced in prostate cancer cell lines and primary tumors, and silenced TIMP-2 gene expression is associated with cancer progression during the invasive and metastatic stages of the disease." (PMID 38276258, 2023). "The target gene of miR-891a-5p is TIMP2, which is associated with proliferation, migration, and tumor formation in prostate cancer." (PMID 37445965, 2023). "Further, hypermethylation of the TIMP2 promoter causes transcriptional repression of TIMP2 levels in many types of tumors, including lymphoma and prostate cancer, resulting in tumor metastasis through MMP activation." (PMID 36624735, 2022). "The GT (TIMP-2 -418∗G/303∗T) haplotype was associated with an increased risk of prostate cancer (OR = 1.78; 95% CI: 1.18-2.69, P = 0.006, Pc = 0.024)." (PMID 31275061, 2019). "Haplotype results demonstrated that TIMP-2 (-418G/303T) was associated with a 1.8-fold increased risk of prostate cancer." (PMID 31275061, 2019). "TIMP-2 -418GC genotype was associated with the reduced risk of prostate cancer (P = 0.037, OR = 0.346)." (PMID 31275061, 2019). "Enhanced amounts of TIMP-2 protein are found to be associated with prostate cancer malignancies, but for colon and gastric cancer the correlation with clinico-pathological parameters has not been established." (PMID 16940985, 2006). "Accumulated research indicated that TIMP-2 genetic variants may influence the risk of various types of cancer, including head and neck cancer, prostate cancer, and gastric cancer." (PMID 38276258, 2023). "Multiple pieces of evidence have linked elevated levels of TIMP-2 with the proliferation, invasion, and/or metastasis of BC, as well as other cancer types such as oral cancer, laryngeal cancer, colorectal cancer, renal cell carcinoma, bladder cancer, and prostate cancer." (PMID 38276258, 2023). "In current study found that apelin increases c-Src phosphorylation, while the c-Src inhibitor or siRNA reversed apelin-regulated TIMP2 synthesis and the motility of prostate cancer cells." (PMID 36291151, 2022). "TIMP2 is reported to be dysregulated in more than 30 clinical studies on breast 26, lung 27, and prostate cancer." (PMID 35414793, 2022). "Apelin suppresses TIMP2 production and subsequently facilitates the metastatic potential of human prostate cancer cells by increasing miR-106a-5p synthesis via the c-Src, PI3K and Akt signaling cascades." (PMID 36291151, 2022). "We observed that apelin promoted prostate cancer cell migration and invasion that was antagonized when the cells were transfected with TIMP2 overexpression." (PMID 36291151, 2022). "Cells were applied with the miR-106a-5p inhibitor reversed apelin-induced regulation of TIMP2 expression and prostate cancer cell motility." (PMID 36291151, 2022). "The analysis of TCGA and GEPIA records as well as IHC data from the tissue array also revealed lower levels of TIMP2 in prostate cancer tissue than in normal healthy specimens." (PMID 36291151, 2022). "In this study, stimulation of prostate cancer cells with apelin abolished TIMP2 expression by a greater extent than TIMP1 or TIMP3, suggesting that TIMP2 is more important than other TIMPs in apelin-mediated motility of prostate cancer cells." (PMID 36291151, 2022). "Our data showed that the PI3K and Akt inhibitor or siRNA antagonized apelin-mediated TIMP2-dependent prostate cancer motility." (PMID 36291151, 2022). "Apelin also appeared to promote the migration and invasion of prostate cancer cells by inhibiting TIMP2 production." (PMID 36291151, 2022). "Our study analyses indicate that compared with normal controls, prostate cancer patients have lower levels of TIMP2 expression." (PMID 36291151, 2022). "Treatment of prostate cancer cells with the c-Src inhibitor (PP2) or siRNA antagonized apelin-regulated effects on TIMP2 expression, cell migration and invasion." (PMID 36291151, 2022).